NMRK1 (nicotinamide riboside kinase 1)
Description:
Catalyzes the phosphorylation of nicotinamide riboside (NR) and nicotinic acid riboside (NaR) to form nicotinamide mononucleotide (NMN) and nicotinic acid mononucleotide (NaMN). The enzyme also phosphorylates the antitumor drugs tiazofurin and 3-deazaguanosine.
Synonyms: C9orf95; NRK1; FLJ20559; bA235O14.2
Tractability: Small molecule: a structure with a bound ligand is known; it has a high-quality binding pocket. PROTAC: ubiquitination databases record sites on it.
Gene: Protein-coding gene on chromosome 9 (75,060,573 to 75,088,306, reverse strand). Ensembl gene ENSG00000106733.
Subcellular location (Human Protein Atlas): Cytosol; Nucleoplasm; Centrosome
Pathways (Reactome):
Metabolism: Nicotinate metabolism
Gene Ontology:
Molecular function: nicotinate riboside kinase activity; protein binding; ribosylnicotinamide kinase activity
Biological process: nicotinate metabolic process; NAD+ biosynthetic process
Cellular component: cytosol
Genetic constraint (gnomAD): Loss-of-function variants: 8 observed, 11.98 expected, observed/expected ratio (o/e) 0.67, 90% interval 0.39 to 1.2. The upper end of that interval is the gene's LOEUF score, 1.2, which puts it in group 5 of 6, group 1 being the genes least tolerant of losing a copy. Missense variants: 128 observed, 138.75 expected, observed/expected ratio (o/e) 0.92, 90% interval 0.8 to 1.07. Synonymous variants: 29 observed, 42.9 expected, observed/expected ratio (o/e) 0.68, 90% interval 0.5 to 0.92.
Homologues: Orthologues: macaque NMRK1 (93% identical), chimpanzee NMRK1 (92% identical), pig NMRK1 (86% identical), dog NMRK1 (83% identical), guinea pig NMRK1 (81% identical), mouse Nmrk1 (79% identical), rat Nmrk1 (79% identical), zebrafish nmrk1 (48% identical), Drosophila melanogaster CG12016 (34% identical). Paralogues in human: NMRK2 (53% identical), MBIP (15% identical), MOCS2 (8% identical).
Diseases named in the same sentence as NMRK1 in open-access papers:
NMRK1 is named in the same sentence as 19 diseases in open-access papers, as found by Europe PMC text mining. Sharing a sentence is not in itself a finding about the gene and the disease. The quoted sentences say what the papers report.
glioblastoma (2 papers, 2019 to 2022). The most malignant astrocytic tumor (WHO grade IV). "We previously found that NAD+ restoration in glioblastoma cells utilizes the salvage pathways via NAMPT and NMRK1, while nicotinic acid phosphoribosyltransferase (NAPRT) and de novo synthesis from tryptophan via quinolinic acid phosphoribosyltransferase (QPRT) are not involved." (PMID 35628596, 2022). "Indeed, we found, overall, higher levels of NAD+-synthesis enzymes NAMPT, NMRK1, and QPRT as well as NADK in primary glioblastomas compared to low-grade gliomas and astrocytes in our and publicly available data, indicating an overall increase in NAD+-biosynthesis in malignant cells." (PMID 31888244, 2019).
glioma (2 papers, 2019 to 2022). A benign or malignant brain and spinal cord tumor that arises from glial cells (astrocytes, oligodendrocytes, ependymal cells). "We previously analyzed the expression levels of the rate-limiting enzymes of the four NAD+ synthesis pathways in glioma cells and astrocytes and found the two salvage pathways via NMRK1 and NAMPT to be the sole contributors to NAD+ synthesis." (PMID 35628596, 2022). "However, NMRK1 expression varied substantially between different glioma cells, thus limiting the clinical practicality of NMRK1-inhibiting approaches." (PMID 35628596, 2022). "Moreover, NAMPT was the only protein also expressed in each of eight patient-derived IDH-mutant and -wildtype glioma cell models; six of them also showing measureable NMRK1 expression." (PMID 31888244, 2019). "As with QPRT, the NMRK1 expression was highly variable between individual glioma cells, with cells displaying no detectable protein levels up to a strong expression." (PMID 31888244, 2019).
viral infection (2 papers, 2020 to 2026). "Notably, NAD biosynthetic gene changes were conserved in vivo with NAMPT and NMRK1 gene expression increased by viral infection in ferrets, and NAMPT increased in the human patient samples." (PMID 33051211, 2020).
Hyperammonemia (1 paper, 2023). An increased concentration of ammonia in the blood. "Lack of NR reversal of ammonia‐induced NAD+ deficiency or lower redox ratio may be related to the unaltered nicotinamide riboside kinase 1 (NRK1) during hyperammonemia (as seen on our bioinformatics analyses) or context‐dependent responses to NR reported in skeletal muscle by others." (PMID 37101412, 2023).
tumor (6 papers, 2019 to 2024). "NMRK1 loss via either gene knock-out or knockdown decreased cellular NAD levels in FK866-treated, NAR-supplemented tumor cells, as did NADSYN1 knock-out." (PMID 38092728, 2023). "The selective vulnerability of IDH1R132H cells to knockdown of NAMPT and NMRK1 indicated that these cells used both pathways to synthesize NAD+, making both enzymes possible targets for the selective treatment of IDH1 mutated tumor cells." (PMID 35628596, 2022). "Moreover, since NAR metabolism requires NMRK1, treatment with a small molecule inhibitor of tumor cell NMRK1 could serve as another option to drive synthetic lethality in the presence of a NAMPTi." (PMID 38092728, 2023). "Although nicotinamide riboside kinase 1 (NRK1) also plays an important role in NAD salvage pathways converting NR to NMN, the prognostic value of NRK1 in tumor needs to be revealed." (PMID 31448236, 2019). "However, NMRGs with significant AUC values (AOX1, SIRT3, NMRK1, PARP1) were differentially expressed among tumor stages." (PMID 38254798, 2024). "Notably, when NAMPT was depleted in salvage-dependent tumors, they were still able to maintain the NAD supply through the alternative salvage NR-NMRK1 pathway, and dual NMRK1 and NAMPT inhibition resulted in more effective NAD reduction and significant tumor suppression in vivo." (PMID 34068917, 2021).
cancer (3 papers, 2020 to 2025). A tumor composed of atypical neoplastic, often pleomorphic cells that invade other tissues. "Notably, we previously showed that top genes of this program (LDHB, GSTK1, DGKA, APRT, MGAT4A, and NMRK1) are predictive of the response of patients with cancer to ICIs." (PMID 40187353, 2025).
infection (2 papers, 2022 to 2026). The state of being infected such as from the introduction of a foreign agent such as serum, vaccine, antigenic substance or organism. "Up-modulation was specific for NAMPT, while the other three NBEs, i.e., NAPRT, NMRK1, and QPRT, were unaffected by infection with BRAF V600E (heatmaps on the right)." (PMID 35272691, 2022).
NMRK1 also shares sentences with these, for which no sentence is quoted: cardiac hypertrophy (2 papers); Glucose intolerance (2); Insulin resistance (2); Sepsis (2); astrocytomas (1); colon cancer (1); liver steatosis (1); metabolic disease (1); non-alcoholic fatty liver disease (1); ovarian carcinoma (1); sarcopenia (1); steatosis (1).